LRCH3 (leucine rich repeats and calponin homology domain containing 3)
Description:
As part of the DISP complex, may regulate the association of septins with actin and thereby regulate the actin cytoskeleton.
Synonyms: MGC4126
Tractability: PROTAC: ubiquitination databases record sites on it; its protein half-life has been measured.
Gene: Protein-coding gene on chromosome 3 (197,791,226 to 197,888,436, forward strand). Ensembl gene ENSG00000186001.
Subcellular location: Cytoplasm
Subcellular location (Human Protein Atlas): Cytosol
Gene Ontology:
Molecular function: protein binding
Biological process: septin cytoskeleton organization; septin ring organization
Cellular component: cytosol; cytoplasm
Genetic constraint (gnomAD): Loss-of-function variants: 49 observed, 71.14 expected, observed/expected ratio (o/e) 0.69, 90% interval 0.55 to 0.87. The upper end of that interval is the gene's LOEUF score, 0.87, which puts it in group 3 of 6, group 1 being the genes least tolerant of losing a copy. Missense variants: 733 observed, 740.87 expected, observed/expected ratio (o/e) 0.99, 90% interval 0.93 to 1.05. Synonymous variants: 269 observed, 292.22 expected, observed/expected ratio (o/e) 0.92, 90% interval 0.83 to 1.02.
Homologues: Orthologues: macaque LRCH3 (97% identical), chimpanzee LRCH3 (96% identical), pig LRCH3 (88% identical), rabbit LRCH3 (85% identical), dog LRCH3 (85% identical), guinea pig LRCH3 (85% identical), mouse Lrch3 (84% identical), rat Lrch3 (83% identical), tropical clawed frog lrch3 (59% identical), Drosophila melanogaster Lrch (31% identical), zebrafish lrch3 (27% identical). Paralogues in human: LRCH2 (42% identical), LRCH1 (40% identical), LRCH4 (39% identical), LRRK1 (26% identical), SCRIB (18% identical), ERBIN (17% identical), LRRC7 (17% identical), PHLPP1 (17% identical), MFHAS1 (14% identical), PHLPP2 (14% identical), PIDD1 (12% identical), LRRC28 (11% identical), and 19 more.
Diseases named in the same sentence as LRCH3 in open-access papers:
LRCH3 is named in the same sentence as 4 diseases in open-access papers, as found by Europe PMC text mining. Sharing a sentence is not in itself a finding about the gene and the disease. The quoted sentences say what the papers report.
colorectal cancer (1 paper, 2020). A primary or metastatic malignant neoplasm that affects the colon or rectum. "In colorectal cancer, a potential complication of ulcerative colitis, expression of LRCH3 is increased compared to colorectal tissues of healthy individuals and expression of LRCH4 is increased in colorectal cancer patient samples with more advanced stages of cancer." (PMID 33072765, 2020).
LRCH3 also shares sentences with these, for which no sentence is quoted: bacterial infection (1 paper); cancer (1); tumours (1).